VEGFA (vascular endothelial growth factor A)
Diseases named in the same sentence as VEGFA in open-access papers (continued):
Sharing a sentence is not in itself a finding about the gene and the disease.
cancer (continued). "VEGFA, PDGFRB, ANGPTL4 and ENG have been shown to play major roles in angiogenesis and vascular homeostasis, not only in physiological regeneration but also in most pathological angiogenic processes such as cancer." (PMID 38882056, 2024). "Consequently, GLI2 and its downstream genes, including cancer stem cell (CSC) transcription factors, vascular endothelial growth factor A (VEGFA) and PDGFA, were upregulated." (PMID 39175990, 2024). "There may be a feed-back loop mediated by VEGFA between TNBC cells and macrophages and this process could be amplified in the development of cancers." (PMID 38169627, 2024). "It is reported that miRNAs that regulate VEGFA and NFE2L2 could serve as the therapeutic targets in various cancers." (PMID 38221932, 2024). "The target genes of miR-140-3p were involved in processes such as the response to growth factors, positive regulation of transferase activity, the VEGFA-VEGFR2 signaling pathway, microRNAs in cancer, and the transforming growth factor beta (TGF-beta) signaling pathway." (PMID 39006969, 2024). "VEGFA+ mast cells are thought to be protumor across several cancer types, although they are largely absent in HCC." (PMID 39761010, 2024). "Additionally, genes such as VEGFA on chromosome 12, and KDR and KIT on chromosome 13, are frequently amplified in these cancers." (PMID 39872607, 2024). "Once cancer cells arrive in the new soft environment of the lung, they release soft EVs that transform the resident fibroblasts toward a CAF phenotype through increased expression of ACTA2, COL1A1, and VEGFA, VIM." (PMID 38630893, 2024). "Notably, up-regulated VEGFA and PGF were observed in 15 cancers, with the highest differences observed in kidney renal clear cell carcinoma (KIRC)." (PMID 37852616, 2023). "The VEGFA-VEGFR2 downstream pathway is related to angiogenesis and vascular permeability, which plays an important role in oncology and represents a potential target signaling pathway for cancer therapy." (PMID 38138609, 2023). "VEGFA monoclonal antibodies and VEGFA receptor targeting drugs mediate immune stimulatory effects independent of ADCC and ADCP, largely reflecting VEGFA’s key role in establishing cancer-related immunosuppression." (PMID 37469408, 2023). "This led to the downregulation of TGFβ-responsive genes, including vascular growth factor A/B (VEGFA/VEGFB), hypoxia-inducing factor 1α (HIF-1α), and thrombospondin 1 (TSP1), all of which play crucial roles in various aspects of cancer progression such as angiogenesis, invasion, and metastasis." (PMID 37894372, 2023). "Vascular endothelial growth factor A (VEGFA) is the dominant and most studied angiogenic factor for the progression of solid cancer tissue; therefore, it is logical that it is also secreted from the cancer cells themselves." (PMID 37998393, 2023). "The increased JAK1 and STAT3 corporately contributed to the activation of the p-STAT3 signaling pathway and further upregulated downstream effectors expressions, including VEGFA and CCND1, which finally resulted in enhanced cancer cell proliferation and metastasis in vitro and in vivo." (PMID 38001065, 2023). "Moreover, VEGFA can promote epithelial-mesenchymal transition (EMT) and metastasis to influence cancer progression." (PMID 37234708, 2023). "According to the results of cell phenotype assays, the JAK1-STAT3 signaling downstream effectors, including VEGFA and CCND1, were screened out and their functions were uncovered in cancer cells, but themselves were also reported as METTL3-modified targets in a recent study." (PMID 38001065, 2023). "Vascular endothelial growth factor A (VEGF-A) and its receptors are known to play a key role in angiogenesis; therefore, targeting the VEGF pathway represents one of the main areas of human cancer research in recent years." (PMID 37999456, 2023).
cancer (continued). "In addition to regulation of cell proliferation and apoptosis, it can affect cancer metabolism and angiogenesis through modulation of a number of targets including GLUT1, VEGFA, and HIF1α." (PMID 37204522, 2023). "Furthermore, CYP4Z1 overexpression promoted the expression of the vascular endothelial growth factor A (VEGF-A) and decreased the expression of the tissue inhibitor of metalloproteinases 2 (TIMP-2) in cancer cells compared to control cells." (PMID 36143940, 2022). "In conclusion, the network pharmacology of this study was used to screen out the active compounds of SBG (baicalein and wogonin), 41 intersection targets (VEGFA, IL6, MAPK3, JUN, TNF, and other targets), and 20 main pathways (Pathways in cancer, IL-17, TNF signaling pathway and others)." (PMID 36415861, 2022). "In addition, NF-κB downstream effectors, such as CCND1, CCNE2, MET, VEGFA, CD44 and CD133, contribute to cancer proliferation, metastasis and stemness, and their expression is regulated by PCDH1." (PMID 35864095, 2022). "Thus, multiple analyses of large cancer datasets have demonstrated a significant (anti) correlation between activities of TGF-β and VEGFA pathways and levels of antitumor immune response." (PMID 35577211, 2022). "A majority of cuproptosis-related genes like CP, MT1E, MT1F, MT1X, VEGFA, and PDK1 were expressed significantly higher on cancer cells, indicating that cuproptosis might occur mainly on cancer cells." (PMID 36211378, 2022). "Network exploration suggested that VEGFA, STAT3, and PI3KCA may be candidate agents for the antibladder cancer effect of gypenosides." (PMID 35402614, 2022). "This study aimed to investigate if the transfection of miR-17-5p, miR-140-5p, and miR-874-3p microRNAs could affect the gene and protein expression of VEGFA, KRAS, and NFE2L2 in two cancer cell lines derived from HNC." (PMID 35806488, 2022). "Aberrant glycosylation is related to cancer cell survival, the induction of angiogenesis, the upregulation of vascular endothelial growth factor A (VEGFA), and changes in the expression and activity of matrix metalloproteinases (MMPs), as well as cancer cell invasion and metastasis." (PMID 36296679, 2022). "VEGFA is the principal angiogenic promoter in most, if not all, cancers acting primarily on endothelial cells through its cognate receptors VEGF-R1 and VEGF-R23." (PMID 35710947, 2022). "Notably, the VEGFA, APLN, and AGT genes were more positively expressed in KIRC cancer cells (qVEGFA=1.7×10−4, qAPLN=1.4×10−13, qAGT=6.1×10−7), and showed substantial regulatory effects on downstream genes of the stroma (q." (PMID 35079698, 2021). "Additionally, circ_0018289 knockdown decreased the levels of angiogenesis inducers VEGFA and FGF2 in the two cancer cell lines." (PMID 34404391, 2021). "Interestingly, the phosphoinositide 3‐kinase (PI3K)/AKT/mTOR signal pathway, one of the most commonly deregulated pathways in human cancers, has been verified to be modulated by PDK1 and VEGFA." (PMID 34431227, 2021). "In the cancer microenvironment DPMSCs secrete pro-adhesive molecules, including BMP2, CX3CL1, and VEGFA, which may regulate the adhesive properties of MDA231 cells through their paracrine effect or through their secretome; this needs to be examined." (PMID 34944000, 2021). "Interestingly, the relative expression levels of estimated paracrine effectors, such as VEGFA, APLN, and AGT, were found to be strikingly and significantly higher in PDX cancer components than in cell lines obtained from CCLE data." (PMID 35079698, 2021). "Moreover, transformation to malignancy is known to change the cancer cell secretome, which often includes a series of immunosuppressive (TGF-β, IL-10), proangiogenic (VEGFA) and CAF inducing (PDGFs, FGF2) growth factors and cytokines." (PMID 34771610, 2021).
cancer (continued). "In addition, hsa-mir-106b-5p also targets genes that play an important role in immunity such as APP, VEGFA, KAT2B, MAPK8, and AGO1 and this miR-mRNA binding allows post-transcription disruption of these genes to influence cancer development." (PMID 33773548, 2021). "Interestingly, VEGFA-LNC and its TSS are conserved in many other cell types, such as THP1 monocytes and MCF-7 cancer cells." (PMID 33875575, 2021). "Therefore, we predicted VEGFA, APLN, and AGT genes as paracrine effectors for the cancer-stroma interaction in KIRCs, whereas DLL4, APP, and TGFB1 genes to be potential autocrine effectors." (PMID 35079698, 2021). "Examples of cancer related genes in the network included GAS6, MAP3K4, PRKD1, PTPRD, and VEGFA." (PMID 34434222, 2021). "VEGFA alternative splicing isoforms have different roles in vascularization and cancer progression, but their expression in CML has not been studied." (PMID 34316716, 2021). "Moreover, using PPI networks, key cancer regulators such as MYC, VEGFA, AKT1, CDKN1A, RHOA, and PTEN are identified." (PMID 33281862, 2020). "Except for those 14 cancer classification marker genes, there were significant differences in the expression of three genes: GLI1 (GLI family zinc finger 1), KRT19 (Keratin 19), and VEGFA." (PMID 33692941, 2020). "Moreover, VEGFA, EGFR, CASP3, AKT1, and CCND1 were identified as hub genes in the antilung cancer of cinobufotalin injection." (PMID 32148531, 2020). "Several studies have documented cross talk between cancer and immune cells, but also inflammatory factors that are expressed by the TME, such as the CSF family of cytokines, which attract macrophages (through CCL2 and VEGFA)." (PMID 33036138, 2020). "To determine the functional relationship between VEGFA and Slug in PCa, we focused on the PI3K/Akt pathway which is a common downstream signaling outcome of activation of the VEGFA/VEGFR2 signaling axis and which plays an important role in cancer cell survival." (PMID 32198489, 2020). "Wnt/β-catenin signaling and expression patterns of important genes in cancer cell growth and survival, which were further suggested to play a role in three-dimensional aggregation, such as NFKB2, VEGFA, CTGF, CAV1, BCL2(L1), or SNAI1, were clearly affected by DEX." (PMID 32033410, 2020). "A total of 155 nodes, including 20 putative targets of HZJD decoction, were selected as core hubs based on topological importance and were closely associated with the regulation of cell proliferation, apoptotic process, and cancer-related pathways (AKT1, TNF, VEGFA, and EGFR) in CAG." (PMID 33354218, 2020). "Network analysis indicated that main targets of main active components of TWH were target genes such as VEGFA, MAPK8 and CASP3, which are involved in the regulation of cancer pathway, TNF signal pathway, hepatitis B pathway, apoptosis pathway, NF-kappa B signal pathway and so forth." (PMID 32293395, 2020). "Until now, there is still no method to effectively block VEGFA production in cancer cells from the very beginning, i.e., from the transcriptional level." (PMID 32550907, 2020). "Recent research supports the role of Hippo signaling in the modulation of cancer-cell proliferation and human tumorigenesis by transcriptional regulation of several cell proliferation-related genes, such as AREG, AXL, CTGF, CYR61, and VEGFA." (PMID 32365528, 2020). "For GI cancer, EGFR, PDGFRA, VEGFA, PDPK1, and MCL1, etc. could be validated as drug targets for anti-cancer drugs." (PMID 32523951, 2020). "We also identified a novel gene associated with the risk of BRONJ that is involved in angiogenesis in patients of cancer BRONJ, PLVAP, which is the VEGFA downstream signaling target involved in the structure of the diaphragm and functions in vascular fenestrations." (PMID 31747953, 2019). "Collectively, these experiments suggested that VEGFA promoted hypoxia‐induced VM formation, which may be mediated by the EMT process and cancer stem cells (CSCs) in SACC cells in vitro." (PMID 30945361, 2019).
cancer (continued). "Neutralizing antibodies targeting VEGFA or the ligand binding site on its receptor, VEGFR2, have been available in the clinic for more than a decade by now and have been tested in many different cancers with relatively limited clinical benefit overall." (PMID 31318171, 2019). "To determine the complex mechanism by which one cytokine is involved in the progression of carcinoma and to explore the possible mechanism of IGFBP5 in KIRP, we identified two key proteins, VEGFA and TGF-β, which are highly related to IGFBP5 and actively participate in carcinoma." (PMID 31886201, 2019). "Remarkably, the expression of IL‐8, TGF‐β, VEGFA, VEGFR1, VEGFR2, and FGF2, which had been described as promoting cancer cell proliferation, is significantly reduced on 2‐FF‐treated cells, suggesting that the decreased growth factors are the underlying mechanism for the reduced cell proliferation." (PMID 29215790, 2018). "Accumulating evidence has shown that VEGFA could bind to its receptor VEGFR2, then activate PI3K and its downstream targets Akt and mTOR, which play crucial roles in cancer progression and survival." (PMID 30476901, 2018). "Moreover, HIF overexpression can activate vascular endothelial growth factor-A, thereby linking glycolysis and LDH to angiogenesis and cancer progression." (PMID 29535837, 2018). "A total of 43 genes reside within 10 kb of these regions (column B), including those involved in cancer pathways (e.g. MMP2), angiogenesis (e.g. VEGFA), hypoxia response (e.g. SCAP), and neural development (e.g. KCNQ2), with downregulation of these loci being the dominant transcriptional effect." (PMID 29587824, 2018). "Furthermore, miR-106b-5p promotes the progression of CC by targeting three key genes (GSK3B, VEGFA, PTK2) through three crucial pathways (PI3K-Akt signaling pathway, focal adhesion, and pathways in cancer)." (PMID 30275981, 2018). "Overwhelming evidences had demonstrated that VEGFA could bind to VEGFR2, then activate PI3K and its downstream target Akt and mTOR which play key roles in cancer proliferation, metastasis, angiogenesis, and survival." (PMID 30250022, 2018). "Finally, it was found that Zm-Ag.NPs inhibited cancer cell metastasis through a decrease in MMP and VEGFA expression." (PMID 29881420, 2018). "Some of these treatments could oppose the deregulations occurring in cancer samples, including those of the CHECK2, CYP51A1, HMGCS1, ITGA2, NME1 or VEGFA genes." (PMID 28962550, 2017). "High intratumor VEGFA correlates with poor outcome for various cancers, but OVCA studies have been limited by small numbers and not all show significance." (PMID 28179359, 2017). "The level of VEGFA mRNAs was not significantly altered in JSRV-induced cancers or the derived-AECII cultures when compared to normal samples." (PMID 29137669, 2017). "The VEGFR1 kinase expression was higher than AXL in MPM, however, the VEGF ligand (VEGFA gene) was not expressed in MPM as high as most other cancers in the dataset (ranking #20 of 30)." (PMID 29375377, 2017). "VEGFA is best known as an angiogenic agent, but it also promotes cancer invasion and metastasis through mechanisms that are not fully understood." (PMID 28504716, 2017). "Examination of RNA-Seq reads from a wide range of tissues and cancer samples revealed sequences derived from the canonical exon 8a-containing VEGFA isoforms in all datasets, but no sequences indicative of any VEGFAxxxb isoform." (PMID 28246395, 2017). "We report the absence of VEGFA proteins in JSRV-induced adenocarcinomas in sheep, while the mRNA level of VEGFA was maintained and not different in normal lungs and cancers." (PMID 29137669, 2017). "Binding of Chelerythrine with BCL2, VEGFA and KRAS genes involved in evasion, angiogenesis and self sufficiency of cancer cells provides a new insight for the development of future therapeutics against cancer." (PMID 28102286, 2017). "Among many oncogenes, VEGFA, BCL2 and KRAS are overexpressed in many types of cancer cells." (PMID 28102286, 2017).
cancer (continued). "Since VEGFA is frequently overexpressed in OVCA and VEGF/VEGFR‐targeted therapies have significant activity in this cancer, we investigated whether VEGFA drives ovarian CSC expansion and sought to identify targetable pathways mediating these effects." (PMID 28179359, 2017). "lncRNA-H19 and circular MYLK as well as circular CTDP1 could regulate the expression of DNMT3B, HAS3, VEGFA and ITGB1 through competing miRNA response elements (MREs) of miRNA-29a-3p, which would result in growth and metastasis of cancer." (PMID 27363013, 2016). "Differently from the current anti-angiogenic drugs (bevacizumab, aflibercept and TK inhibitors) used to treat cancer patients, iVR1 does not interfere with the VEGFA/VEGFR2 pathway." (PMID 25868854, 2015). "While CCND2, a cell cycle regulator, VEGFA, an essential regulator of angiogenesis in a variety of cancer types and BRAF, an oncogene in a variety of cancers, most likely serve as our “proof of concept” genes for demonstrating functional significance in human ERMS." (PMID 24009521, 2013). "Taken together, all these observations might suggest to further investigate the usefulness of VEGFA, MET and TFRC as common cancer biomarkers." (PMID 22761861, 2012). "Consistent with our findings, a high expression of VEGFA as well as an association with poor prognosis have previously been found in malignant tumours including EOC, indicating that VEGFA may be a possible prognostic marker." (PMID 23029477, 2012). "The highest concentrations of serum VEGFA were founded in metastatic breast cancer, in particular among patients who did not receive cancer therapy for metastatic disease." (PMID 23203097, 2012). "Interestingly, in non-cancer-affected controls, all gene-to-gene correlations were positive and strong in pre-menopausal cases and were either moderate for VEGFA and EPAS1 or not significant for other gene-to-gene correlations in post-menopausal." (PMID 39888575, 2026). "However, interactions between angiogenesis (VEGFA) and cell cycle regulation (CDKN1A) may be plausible given their roles in processes like cancer, where dysregulation of both blood supply and cell proliferation is common." (PMID 41554049, 2026). "Network analysis highlighted VEGFA and SRC as potential key targets, with functional annotation and KEGG enrichment analyses indicating that silymarin may modulate multiple pathways, including the VEGF signaling pathway and proteoglycans in cancer." (PMID 39852395, 2025). "Ang II stimulates vascular endothelial growth factor A (VEGF-A) expression through the epidermal growth factor receptor (EGFR), mitogen-activated protein kinase (MAPK), extracellular signal-regulated kinase (ERK1/2), and PI3K/AKT pathways, facilitating neovascularization in various cancers." (PMID 40722848, 2025). "Moreover, except for PD‐L1 and VEGFA, our study found that YTHDF2 modulates many crucial genes involved in cancer‐associated signaling pathways (data not shown), implying critical role of YTHDF2 in HCC progression and calling for further researches." (PMID 38247171, 2024). "Furthermore, ID4/ VEGFA/ VEGFR2/ integrin β3 signaling stimulates the nuclear translocation and activation of the Hippo pathway member’s YAP and TAZ, two critical executors for cancer initiation and progression." (PMID 38321003, 2024). "Together, these results suggest that soft vesicles produced by newly disseminated cancer cells in the soft microenvironment of the lung are significantly more effective at producing a CAF-like phenotype in lung fibroblasts via ensuing upregulation of S100 inflammatory signals and ACTA2//VEGFA/VIM." (PMID 38630893, 2024). "Therefore, there may be a feedback loop mediated by VEGFA between TNBC cells and TAMs, and this process could be amplified in the development of cancers." (PMID 38169627, 2024).